TRGVA (T cell receptor gamma variable A (pseudogene))
Synonyms: V5P; formerly TCRGVA
Gene: T-cell receptor variable (V) pseudogene on chromosome 7 (38,322,446 to 38,322,730, reverse strand). Ensembl gene ENSG00000225992.
Diseases named in the same sentence as TRGVA in open-access papers:
TRGVA is named in the same sentence as 2 diseases in open-access papers, as found by Europe PMC text mining. Sharing a sentence is not in itself a finding about the gene and the disease.
TRGVA shares sentences with these, for which no sentence is quoted: prostate tumors (1 paper); tumor (1).